ATM (ATM serine/threonine kinase)
Diseases named in the same sentence as ATM in open-access papers (continued):
Sharing a sentence is not in itself a finding about the gene and the disease.
melanoma (continued). "The implication of ATM in melanoma development is recent, but the activation of the ATM/ATR pathway in response to UV-induced replication stress has been documented." (PMID 34262154, 2021). "Here, we demonstrated that ATM LOF variants are more frequent in melanoma patients than in NFE subjects in the gnomAD database, seemingly conferring moderate risk, supporting ATM as a melanoma predisposition gene." (PMID 34262154, 2021). "Another recent analysis of human melanoma found that 21.4% of this tumor type has at least one HRD gene mutation including BRCA1, ARID1A, ATM, ATR and FANCA." (PMID 34885093, 2021). "Accordingly, patients with metastatic stage III melanoma tumours had a significantly higher mRNA expression for RAD50, NBS1, MRE11 and ATM as compared to patients with primary melanoma." (PMID 34709752, 2021). "Our patient who carried the ATM variant had an IDC at 38 years and reported a family history of cancer, in particular, the father deceased for melanoma at 65 years." (PMID 32365798, 2020). "A total of 9 patients (3.4%) carried mutations in high-to-moderate melanoma risk genes (CDKN2A, POT1, ACD) and 22 (8.3%) patients in other cancer syndrome genes (NBN, BRCA1/2, CHEK2, ATM, WRN, RB1)." (PMID 33050356, 2020). "Performing germline/tumour whole-exome sequencing of 44 stage III/IV melanoma patients we identified pathogenic germline mutations in CDKN2A, CDK4, ATM, POLH, MRE11A, RECQL4 and XPC, affecting 7/44 patients." (PMID 33077847, 2020). "Second, we demonstrate that PP2A depletion or inhibition by phendione induces ATM activation and the DNA damage response, leading to growth inhibition of melanoma that display intrinsic and acquired resistance to MAPK inhibitors." (PMID 32241802, 2020). "Therefore, further studies are needed to determine whether ATM is a risk factor for melanoma." (PMID 32325837, 2020). "Therefore, the mutation of ATM in HT-144 cells could slow down the response to the (Bu3Sn)4TPPS compound used in these experiments that probably, for its high DNA binding affinity, induces DNA damage in melanoma cells." (PMID 31801187, 2019). "We noted that other genes involved in sensing DNA damage and repairing double stranded breaks (e.g. PARP1, ATM, APEX1) are in linkage disequilibrium with SNPs associated with melanoma risk in GWAS." (PMID 30681412, 2019). "Taken together with this study, our findings contribute to a new understanding of UV irradiation on human skin and provide a promising approach for the prevention of angiogenesis-related skin damage and melanoma progression by targeting ATM and SerRS." (PMID 31766690, 2019). "As expected, application of tRA together with the ATM inhibitor greatly reduced the VEGFA expression in melanoma xenografts." (PMID 31766690, 2019). "In line with the results from endometrial cancer patients, analysis of ATM expression (mRNA and protein) in melanoma reported an upregulation of ATM in nodular malignant melanoma samples." (PMID 26275218, 2015). "Tissue microarray and immunohistochemical analysis were employed to study the expression of p-ATM in melanoma patients." (PMID 26275218, 2015). "In order to verify the association between p-ATM expression and melanoma progression, we divided the cases based on AJCC stage and analyzed the correlation between p-ATM and AJCC stage." (PMID 26275218, 2015). "Our multivariate analysis data is also encouraging for additional research on the use of ATM inhibitors for treating melanoma." (PMID 26275218, 2015). "Considering the significance of phosphorylation in monomerization and activation of ATM, there is a need for a clear analysis on the correlation between p-ATM expression and melanoma patient survival." (PMID 26275218, 2015). "Using tissue samples collected from melanoma patients, we analyzed phospho-ATM (ser-1981) expression in melanoma patients and studied the correlation with disease progression and patient survival." (PMID 26275218, 2015).
melanoma (continued). "The present study was therefore performed to understand the significance of p-ATM in melanoma progression and to correlate it with patient prognosis." (PMID 26275218, 2015). "Treatment with forskolin increased the radiation-induced phosphorylation of the PP2A B56δ subunit and decreased the radiation-induced phosphorylation of ATM in the melanoma cells." (PMID 24568192, 2014). "We therefore treated our three SPR-proficient melanoma strains with siRNA pools specifically targeting DNA-PKcs (DNA-PK catalytic subunit), ATM, ATR, or Chk1." (PMID 24416382, 2014). "KU55933 blocked phosphorylation of the ATM target protein Chk2 and impaired senescence in drug-treated melanoma cells, suggesting that ATM/Chk2 mediates drug-induced senescence." (PMID 23180582, 2013). "Transcripts associated with BRCA1, BRCA2, ATM and CHEK2 showed altered expression in melanoma cell lines after cisplatin treatment." (PMID 23940574, 2013). "One previous study by Meng and Jiang showed that PLAB induced G2 phase arrest in SK-28 melanoma cells via activation of ATM signalling pathway." (PMID 22778780, 2012). "Overall, our study provides new and valuable insights into the function of PARP4 and melanoma pathogenesis and suggests that ATM inhibitor may be a promising therapeutic approach for treating melanoma with low PARP4 expression." (PMID 39885134, 2025). "Importantly, PARP4 knockdown enhanced melanoma cell sensitivity to ATM inhibitors in vitro and in vivo, suggesting the potential of exploiting synthetic lethality as a therapeutic strategy." (PMID 39885134, 2025). "Together, these data do not support any predisposition of carriers of the ATM Ser49Cys allele for melanoma or to alteration in an individual’s naevus properties." (PMID 38338943, 2024). "Signature 3 in TWT melanoma tumors is associated with downregulation of ATM and methylation of INO80; however, the source of ATM downregulation is unknown." (PMID 38758740, 2024). "Together, these data do not support any predisposition of carriers of the ATM Ser49Cys allele for melanoma." (PMID 38338943, 2024). "While this signature is associated with BRCA1/2 mutations and double-strand break (DSB) repair deficiency in certain cancer types, it has also been shown to be associated with downregulation of ATM and other genes that function early in the DSB repair pathway in melanoma." (PMID 38758740, 2024). "Taken together, we conclude that especially the difficult-to-treat patients with melanoma that developed MAPKi treatment resistance may benefit from PARPi treatment, and that ATM might be a promising biomarker for treatment response." (PMID 37674529, 2023). "Downregulation of ATM in MAPKi resistant melanomas compared with the treatment-naïve tumors was confirmed by database analysis of mRNA sequencing data from matched melanoma samples before and after either BRAFi resistance or BRAFi/MEKi dual resistance development published by Hugo and colleagues." (PMID 37674529, 2023). "Furthermore, we show for the first time that MAPKi resistant melanoma cell lines and patient material have decreased ATM expression, and this confers sensitivity to PARPi treatment." (PMID 37674529, 2023). "According to previous studies conducted on non-melanoma cancers, this variant results in the skipping of ATM exons 26–27, with impaired/absent protein function." (PMID 36555667, 2022).
melanoma (continued). "Notably, ATM PVs frequency was 5.4% in patients with a family history of PC (3/55) and 3.3% in patients with personal or family history of melanoma (1/30)." (PMID 36139606, 2022). "In addition, Bhandaru and colleagues suggested a possible correlation between the expression of phosphorylated ATM, melanoma progression and patient survival." (PMID 35563772, 2022). "Since these individuals were recruited mainly based on their personal and family history of melanoma, it is therefore unlikely that an enrichment of families with ATM-related tumors may have biased our results." (PMID 34262154, 2021). "Melanoma cells with ILF2‐OV showed a significant upregulation in ATM mRNA levels." (PMID 34709752, 2021). "The association between variants in ATM and melanoma risk is not well established although ATM is associated with a low-to-intermediate risk of other cancers." (PMID 34573422, 2021). "This study is part of a broader project aimed at fully exploring the link between ATM and melanoma." (PMID 34262154, 2021). "IFN-γ derived from immunotherapy-activated CD8+ T cells synergizing with radiotherapy-activated ataxia-telangiectasia mutated (ATM) suppresses SLC7A11, to induce cystine uptake, enhance tumor lipid oxidation and ferroptosis in human fibrosarcoma and melanoma cells." (PMID 34858857, 2021). "Furthermore, we showed that ILF2‐U2AF2 complex enhanced RAD50 and ATM expression in metastatic melanoma cells." (PMID 34709752, 2021). "Recent studies, including the largest meta-analysis of melanoma genome-wide association studies (GWAS) to date, have linked specific low-risk variants in ATM with melanoma, although the functional alleles have not yet been determined." (PMID 34262154, 2021). "One sporadic melanoma MITF-E318K carrier resulted wild-type for CDKN2A and MC1R genes and displayed only germline variants of unknown significance in ATM and Fanconi anemia complementation group I (FANCI) genes." (PMID 34573422, 2021). "However, although underpowered, a case–control analysis limited to the centers that provided ethnically matched controls showed an enrichment of ATM LOF variants and VUS in high-risk melanoma cases, consistent with the results from the main analyses." (PMID 34262154, 2021). "In melanoma cell lines, P22077 treatment remarkably activated the ATM/ATR signalling pathway." (PMID 34469054, 2021). "The LP ATM variant c.875C>T was indeed detected in a 44-year-old woman (P29) with a well-differentiated and hormone-responsive in situ ductal carcinoma (DCIS) diagnosed at 43 years, who had removed a melanoma a year before." (PMID 32957588, 2020). "Taken together, these results pinpoint phendione as an inhibitor of PP2A whose effects manifest in increased ATM phosphorylation and activation of the DNA damage response, leading to impaired growth of melanoma cells with acquired resistance to MAPK inhibitors." (PMID 32241802, 2020). "Interestingly, our study cohort showed a higher rate of ATM variants than that reported in recent WES and WGS studies that included melanoma." (PMID 32325837, 2020). "p-ATM staining and clinicopathological characteristics of 366 melanoma patients." (PMID 26275218, 2015). "In summary, nuclear p-ATM expression has prognostic significance and may be a potential biomarker and molecular target for melanoma treatment." (PMID 26275218, 2015). "More studies with more patient information could conclusively determine the usefulness of ATM inhibition in the treatment of melanoma." (PMID 26275218, 2015). "Moreover, our study also suggests that the ATM inhibitor may represent a potential therapeutic approach for treating melanoma with low PARP4 expression, offering a potential avenue for individualized treatment strategies." (PMID 39885134, 2025).
melanoma (continued). "However, while analysis of the UK Biobank data reveals that although the ATM p.S49C is not more frequent in melanoma cases as compared to controls, the MITF Glu318Lys variant is significantly more frequent is cases versus controls (p = 1.15 × 10−10)." (PMID 38338943, 2024). "Also, phase II clinical trials checking the efficacy of PARPi treatment in patients with cancer with among others somatic or germline ATM gene mutations, are currently underway (NCT04042831, NCT03344965, NCT02286687, NCT04030559), even for patients with melanoma (NCT03925350, NCT04633902)." (PMID 37674529, 2023). "Furthermore, downregulation of the TAp73 isoform in MAPKi resistant melanoma cells might have an influence on ATM expression." (PMID 37674529, 2023). "In addition, we analyzed a melanoma tissue sample from one patient (Mel_15) with a somatic ATM variant classified as tier 1 and no germline variants." (PMID 36555667, 2022). "However, ATM loss of heterozygosity (LOH) has never been investigated in melanoma and, therefore, a causal association with melanoma development has not been established yet." (PMID 36555667, 2022). "In 2 out of 3 patients carrying PVs, the ATM protein was absent in melanoma tissue, hence supporting the hypothesis that loss of ATM tumor suppressor function is involved in melanoma development." (PMID 36555667, 2022). "In consideration of personal and family history, the presence of the ATM variant was reported to the proband in a research context, with emphasis on the uncertainty about the role of ATM in melanoma and PC development and the absence of a standardized surveillance protocol." (PMID 32325837, 2020). "Therefore, PC occurrence in these families may only partially explain this high detection rate, although one ATM positive patient developed both melanoma and PC." (PMID 32325837, 2020). "Therefore, we hypothesized that the combined application of tRA with the ATM inhibitor might greatly inhibit the progression of melanoma by targeting the UV–ATM–SerRS–VEGFA signaling pathway to suppress tumor angiogenesis." (PMID 31766690, 2019). "Interestingly, strong as well as negative p-ATM expression was found to be significantly associated with resistance to chemotherapy in melanoma patients (p = 0.0194)." (PMID 26275218, 2015). "Previously, strong ATM expression was reported in nodular metastatic melanoma patients and our data showing a correlation between strong p-ATM expression and metastatic melanoma supports the hypothesis that ATM is involved in melanoma metastasis." (PMID 26275218, 2015). "In BL6-10 melanoma cells, reduced expression of ATR, ATM, and CDK1/2 during the transition from the S-phase to the G2-phase has been observed under microgravity conditions, which corresponds with a notable decline in the population of G2-phase cells." (PMID 41513600, 2026). "ATM Ser49Cys, GOLM1 Ser307Leu and MITF Glu318Lys all occur in higher frequencies in melanoma-affected populations (2.3%, 2.9% and 1.6–2.8%, respectively) as compared to general populations (~0.2% and 0.6–0.8%, respectively)." (PMID 38338943, 2024). "In conclusion, this study shows that PARP inhibitor treatment is a valuable therapy option for patients with melanoma, either as a single treatment or as a combination with MAPK inhibitors depending on ATM expression." (PMID 37674529, 2023). "Chalcone 1C significantly induced phosphorylation of ATM in A2058 and BLM melanoma cells in a time-dependent manner (24, 48 and 72 h)." (PMID 36293123, 2022). "When melanoma cells are treated with CRO15, ATM phosphorylation is observed during early stimulation, which induces activation of the DNA damage pathway response." (PMID 33431809, 2021). "The level of pPLK1 was significantly higher in S/G2 phases in both AURKA over-expressing cell lines, and similarly elevated in ATM defective and PPP6C mutant melanoma cells." (PMID 33993200, 2021).
melanoma (continued). "In summary, high levels of ILF2‐U2AF2 protein complex control melanoma progression by upregulating the mRNA and protein expression of RAD50 and ATM." (PMID 34709752, 2021). "To investigate the defective ATM checkpoint function produced by dysregulated AURKA- PLK1 pathway, we stably over-expressed wild type AURKA in two ATM checkpoint functional melanoma cells lines, A2058 and A375." (PMID 33993200, 2021). "TAP-nanoemulsion triggered apoptosis of human malignant melanoma in the lung by inhibiting Bcl-2, cyclins D1 and E, NF-κB, ERK, MEK, and MMP-1 and MMP-9 and increasing cleaved caspase-9 and caspase-3, ATM, and p21." (PMID 32908627, 2020). "Levels of ATM, AMFR, CD109, and SOS1 were all significantly higher (p < 0.001) in plasma samples from either stage 0, stage I/II, or stage III/IV melanoma patients than in healthy controls (respectively), consistent with the NGS data (Table A1)." (PMID 30634628, 2019). "Upon LOXL3 depletion, melanoma cells display a faulty DNA damage response (DDR), characterized by ATM checkpoint activation and inefficient ATR activation leading to the accumulation of double-strand breaks (DSBs) and aberrant mitosis." (PMID 29229995, 2018). "Such a ROS-induced repression of mTOR triggering autophagy was described in a melanoma cell line, whereby ATM activates AMPK via the AMPK kinase and ATM effector LKB1 (also known as STK11)." (PMID 28213588, 2017). "In addition, the phosphorylation levels of ATR, ATM, and BRCA1 were significantly increased after 4 Gy X-ray irradiation in B16 and S91 melanoma tumors." (PMID 37507394, 2023). "Clonogenic survival indicated a clear radiosensitizing effect of the ATM inhibitor (ATMi) AZD0156 in all melanoma cells in a synergistic manner, but not in healthy tissue fibroblasts." (PMID 36229655, 2023). "Our assumption is supported by calculation of the Bliss score of the cell survival data, which shows particularly significant synergisms between RT and ATM inhibition with AZD0156 in most of the melanoma cell lines, but not in healthy cells." (PMID 36229655, 2023). "We demonstrated that MAPKi resistant melanoma cells did not respond to inhibition of ATM by Ku-55933, whereas the inhibitor showed marked cytotoxicity in MAPKi sensitive cells." (PMID 37674529, 2023). "In this paper, we will depict the current evidence on the effect of PARP, ATM, CHK1, WEE1 and ATR inhibitors both in preclinical and clinical settings in melanoma, both as monotherapy and in combination with other targets belonging to the pathways crucial for melanoma proliferation and survival." (PMID 35563772, 2022). "For one of these variants—the founder p.Ser1135_Lys1192del—our results confirm, in melanoma, the negative effect on the ATM protein reported in previous studies." (PMID 36555667, 2022). "Chemotherapeutic drugs or oxidative stress induced DNA damage engage PARP-1/ATM/NF-κB signaling cascade to induce senescence in melanoma and non-melanoma cells." (PMID 33855023, 2021). "Finally, novel inhibitors of other DDR gene alterations are currently undergoing early phase trials to assess their safety and efficacy in melanomas with HRD (i.e., inhibitors of ATR, ATM, CHK1/2, and WEE1, among others)." (PMID 34831002, 2021). "The increase in negative and strong p-ATM expressions was obvious and statistically significant (p = 0.025) from primary melanoma to metastatic melanoma." (PMID 26275218, 2015).